INS (insulin)
Diseases named in the same sentence as INS in open-access papers (continued):
Sharing a sentence is not in itself a finding about the gene and the disease.
type 2 diabetes (continued). "Particularly, patients with diabetes type 2 might benefit from conditioning with intranasal insulin as an US because intranasal insulin has been shown to have a number of benefits for patients with diabetes type 2." (PMID 37234022, 2023). "Synthetic thiazolidinediones (TZDs) and PPAR-γ agonists, including rosiglitazone and pioglitazone, could effectively improve insulin sensitivity and lower the blood glucose level in patients with Type 2 diabetes." (PMID 37686366, 2023). "Like other MAPKs, MAPK8 may affect insulin signaling and, therefore, play a role in the pathophysiology of type 2 diabetes." (PMID 37569434, 2023). "A decrease in MAPK8 gene expression in type 2 diabetes pancreatic beta cells could be due to, on the one hand, a shift in insulin signaling and glucose transport into the cell and, on the other hand, a decrease in chaperone activation and protein folding." (PMID 37569434, 2023). "Genetically predicted higher TG was associated with higher type 2 diabetes risk, HbA1c and fasting insulin in women, but not men." (PMID 36624450, 2023). "Proinsulin, a precursor to insulin produced in pancreatic beta cells, may have elevated levels relative to insulin in individuals with prediabetes and type 2 diabetes due to increased demand for beta cells for insulin release." (PMID 38075044, 2023). "To further investigate the relationships between FINS levels and IAs in insulin-treated type 2 diabetic subjects, we divided 779 subjects with C-INS into four groups according to their direct FINS levels: group 1, ≤ 15μIU/mL; group 2, 15–30μIU/mL; group 3, 30–45μIU/mL; and group 4, > 45μIU/mL." (PMID 37324170, 2023). "Haus and colleagues were among the first to compare the levels of ceramide species in the circulation of patients with type 2 diabetes to those in healthy controls and to determine whether they correlate with insulin sensitivity and plasma TNF concentrations." (PMID 37762318, 2023). "Furthermore, co-treatment with a GLP-1R agonist and a GIPR agonist results in more insulin sensitivity, glucose reduction, food intake reduction, and body weight reduction than either agonist alone in obese mice with type 2 diabetes." (PMID 36909312, 2023). "GLP-1RAs generally do not cause hypoglycemia in patients with type 2 diabetes who are not taking insulin." (PMID 37701904, 2023). "One might speculate that in humans, reversal of the earlier stages of senescence may be the basis of the remission from type 2 diabetes seen with intensive treatment with insulin or gastric bypass." (PMID 37822597, 2023). "In general, improvements in tissue-specific insulin sensitivity in type 2 diabetes may result from reductions in lipotoxic insulin signalling, low-grade inflammation, and oxidative and/or ER stress." (PMID 36178534, 2023). "Insulin sensitivity can be improved by regular exercise, mitochondrial-targeted antioxidants, and counted caloric diet consumption, which can further manage mitochondrial functioning and improve type 2 diabetes." (PMID 37109219, 2023). "Previous studies have shown that iron overload is an important risk factor for type 2 diabetes and that excess iron has a serious negative impact on insulin secretion." (PMID 37090106, 2023). "CCR5+M are related to neuroinflammation and insulin insensitivity, therefore the greater adhesion capacity of CCR5+M in SAs with central obesity provides insight as to why SAs have higher type 2 diabetes risk compared with WEs for any given BMI." (PMID 38011590, 2023). "In individuals with type 2 diabetes with chronic hyperglycaemia or in those treated with sulfonylureas, pancreatic beta cells are chronically depolarised, which in turn leads to a switch from Gas to Gaq as the major pathway for stimulating insulin secretion." (PMID 37430117, 2023). "However, for women with type 2 diabetes that are on insulin during pregnancy, they also expressed similarly going to great lengths to ensure optimal glycemia." (PMID 37131168, 2023).
type 2 diabetes (continued). "Patients with type 1 and type 2 diabetes who require insulin may experience less hypoglycemia when taking long-acting basal insulin, such as insulin degludec." (PMID 38022365, 2023). "Also, dietary substitution was effective for managing obesity and type 2 diabetes; the approach improved fat quality, blood pressure, glycosylated hemoglobin, insulin, and other indicators." (PMID 36997952, 2023). "Thiazolidinediones are insulin sensitizers used for the treatment of Type II diabetes." (PMID 37366179, 2023). "Finally, the use of computerized decision support for insulin dosing in type 2 diabetes yielded a high level of agreement with standard clinical assessments (97%) and was perceived to precipitate a reduction in treatment decision-making errors." (PMID 36780222, 2023). "In pregnancy, patients with type 2 diabetes are mainly treated with insulin or metformin." (PMID 37881498, 2023). "While in the presence of 100 nM insulin, crocetin showed a synergistic Akt phosphorylation-improving effect, suggesting that crocetin might be an insulin-sensitizing agent to treat type 2 diabetes." (PMID 38004168, 2023). "Recent evidence suggests that oxytocin also plays other metabolic roles such as regulation of food intake, peripheral glucose uptake, insulin sensitivity, β-cell function and survival, and insulin secretion, which prompted investigating the implication of oxytocin pathway in type 2 diabetes (T2D)." (PMID 37047255, 2023). "Thus, we examined the insulin doses required to achieve euglycemia in insulin-treated type 2 diabetes patients with SGLT2 inhibitors and the CRIC diet." (PMID 36804863, 2023). "But, in type 2 diabetes, the endogenous insulin production is either normal or higher than normal." (PMID 37663700, 2023). "In addition, type 2 diabetes reduces insulin action and secretion, which results in the decreased inhibition of lipolysis in adipose tissue, raising blood fatty acid levels and increasing the delivery of fatty acids to the liver." (PMID 37623224, 2023). "MR findings indicated a correlation between linoleic acid levels and the risk of type 2 diabetes, fasting blood glucose, and glycated hemoglobin (HbA1c), but not with fasting insulin." (PMID 38075067, 2023). "The question arises whether the ability of GIP and/or GLP-1 to augment glucose-induced insulin secretion translates into an ability to lower plasma glucose in individuals with type 2 diabetes." (PMID 37430117, 2023). "Insulin therapy is critical for patients with type 1 diabetes and may also be required for patients with type 2 diabetes if other treatments are insufficient." (PMID 37623480, 2023). "Given that insulin secretion is impaired in Type 2 diabetes (T2D), it was initially assumed that drugs that stimulate GK activity might enhance insulin secretion." (PMID 39872624, 2023). "This study aimed to evaluate whether the pathways of carbohydrate availability changes has any effect on insulin requirement and macronutrient substrate utilization with energy expenditure in type 2 diabetes, requiring multiple daily insulin injections." (PMID 36804863, 2023). "Type 2 diabetes is a syndrome characterized by chronic hyperglycemia due to decreased insulin action in target organs as a consequence of insulin resistance and insufficient compensation of insulin secretion." (PMID 37852976, 2023). "Therefore, the CIMT trial is the hitherto largest and longest randomised clinical trial assessing the effects of metformin in addition to insulin in people with type 2 diabetes on quality of life, well-being, and development of cardiovascular complications." (PMID 36923108, 2023). "By decreasing lymphocyte infiltration, enhancing insulin-mediated insulin sensing in beta cells, and reducing plasma glucose in lean diabetic mice, LZ-8 may play a significant role in type 2 diabetes." (PMID 36985818, 2023).
type 2 diabetes (continued). "Improved Glucose Control with Weight Loss, Lower Insulin Doses, and no Increased Hypoglycemia with Empagliflozin Added to Titrated Multiple Daily Injections of Insulin in Obese Inadequately Controlled Type 2 Diabetes EMPA-REG MDI Trial Investigators." (PMID 37377258, 2023). "Indeed, we wanted to create a model of obesity that are insulin and glucose intolerant that progress to type II diabetes in the early adult age to evaluate early changes and early events responsible of obesity complications." (PMID 37885804, 2023). "According to a previous study, Parasutterella is positively associated with body mass index, fasting insulin, and type 2 diabetes, independent of low-grade inflammation." (PMID 37260381, 2023). "Type 2 diabetes (T2D) is a chronic inflammatory disease that results from increased blood glucose and lipid levels due to insufficient insulin production by β-pancreatic cells in response to different insulin concentrations." (PMID 37153436, 2023). "Type 1 diabetes is caused by low or no insulin production by the pancreas and Type 2 diabetes results from the body’s inability to produce enough insulin or its ineffective use of insulin." (PMID 37893284, 2023). "The objective of the present study was to investigate insulin-releasing and glucose-lowering actions of EEAA through in vitro and in vivo studies to explore its underlying mechanism of action for the treatment of Type 2 diabetes." (PMID 37133312, 2023). "Accordingly, women treated with insulin in pregnancy have a 3‐fold increased risk of type 2 diabetes progression, compared with women with GDM who did not require insulin treatment." (PMID 36635082, 2023). "Failure to accurately diagnose T1D could lead to life-threatening diabetic ketoacidosis, and inaccurate diagnosis of T2D could lead to unnecessary treatment with insulin when other more appropriate options may be available." (PMID 37841955, 2023). "Until late 2021, children diagnosed with type 2 diabetes could only benefit from metformin and insulin." (PMID 37371671, 2023). "Development of type 2 diabetes has been perceived as a process that involves progressive insulin resistance in muscles, adipose tissue, and liver and a gradual failure of pancreatic beta cells to secrete sufficient amounts of insulin to compensate for the resistance." (PMID 36752854, 2023). "One may therefore speculate that HBO-induced stimulation of insulin sensitivity and mitochondrial function occurs at least partly via mitohormesis (i.e. low-dose ROS-mediated improvement of metabolic pathways) in type 2 diabetes." (PMID 36178534, 2023). "The analysis focuses on assessing the cost-effectiveness of IDegLira compared to other treatment regimens (liraglutide, degludec) for poorly controlled patients with type 2 diabetes who are currently receiving basic insulin therapy, from the perspective of a Chinese healthcare payer." (PMID 37598203, 2023). "However, it is unclear if these effects are confined to insulin secretion and are of sufficient magnitude to alter glucose metabolism, or if the effect size is altered by type 2 diabetes." (PMID 37751301, 2023). "However, in patients with obesity and type 2 diabetes, muscles become unresponsive to insulin action to increase glucose oxidation." (PMID 37865313, 2023). "Insulin, sulfonylureas, and thiazolidinediones have been used to treat type 2 diabetes." (PMID 37374154, 2023). "Furthermore, IRS-1 expression was decreased in type 2 diabetes and obesity subjects, and low IRS-1 expression causes a decrease in insulin-stimulated glucose uptake." (PMID 37711887, 2023). "The type 2 diabetic rat model was established using a high-fat diet combined with low-dose streptozotocin injection and the GF model was induced by using staggered glucose and insulin injections daily." (PMID 37891701, 2023).
type 2 diabetes (continued). "We validated our genetic knockdown results using pharmacologic agents, via selective SSTR3 antagonism which as a therapeutic approach has shown promise as a treatment for type 2 diabetes by boosting insulin secretion in preclinical models and in human islets ex vivo." (PMID 37660302, 2023). "Indeed, hyperglycemia has become somewhat synonymous with reduced insulin secretion or sensitivity, given the prevalence of type I and type II diabetes, respectively." (PMID 36834669, 2023). "In addition, MFGM improved body weight, fasting blood glucose, and serum insulin levels in type 2 diabetic (T2D) mice." (PMID 36978962, 2023). "In this context, we hereby present evidence showcasing the resilience of variant glucokinase proteins of maturity-onset diabetes of the young type 2 (MODY2) against degradation and, concomitantly, their influence on insulin secretion, both in cell lines and in the afflicted MODY2 patient." (PMID 37958824, 2023). "Pathway analyses confirmed a functional role of the identified DNA methylation signals by identification of gene expression being involved in several pathways, including type II diabetes mellitus, insulin signaling, growth hormone synthesis, immune system, and cell signaling pathways." (PMID 36627699, 2023). "The compromised ability of brain cells to appropriately respond to insulin, observed in conditions like type 2 diabetes, could directly hamper their capacity to obtain energy and function optimally." (PMID 38002034, 2023). "Vildagliptin 50 mg QD was effective when combined with insulin therapy in patients with severe renal impairment and long-term type 2 diabetes; reductions in HbA1c were similar to those previously reported among patients with recently developed type 2 diabetes with normal renal function." (PMID 37378205, 2023). "Here we explore whether epigenetic alterations in human pancreatic islets impact insulin secretion and type 2 diabetes (T2D)." (PMID 38086799, 2023). "In this randomized clinical trial conducted at 4 primary care clinics at an academic medical center from March 1, 2021, to December 31, 2022, 32 adults with type 2 diabetes requiring initiation or adjustment of once-daily basal insulin were followed up for 8 weeks." (PMID 38039007, 2023). "In the streptozotocin-nicotinamide model of type 2 diabetes, the encapsulated myricitrin restored blood glucose and insulin levels and improved the total antioxidant capacity and levels of MDA, antioxidant enzymes (SOD, catalase), and apoptotic markers in the pancreas." (PMID 38137892, 2023). "Moreover, Leucine has been shown to benefit lipid metabolism, and insulin sensitivity, making it a promising strategy for preventing and treating metabolic diseases, including type 2 diabetes and obesity." (PMID 38046946, 2023). "Furthermore, several studies have investigated the response to hypoglycaemia induced by human soluble insulin under hyperinsulinaemic–hypoglycaemic clamp conditions in individuals with type 2 diabetes." (PMID 37308751, 2023). "Notably, in individuals with type 2 diabetes, plasma sIR levels exhibit an inverse correlation with insulin sensitivity." (PMID 38069105, 2023). "Moreover, oral administration of BAIBA for 4 weeks in type 2 diabetic mice resulted in improved insulin signaling, by restoring Akt-IRS-1 (Tyr632 and Ser307) phosphorylation." (PMID 37780967, 2023). "For individuals with vitamin D deficiency, supplementation with vitamin D may reduce the incidence of type 2 diabetes, further supporting the potential beneficial effect of vitamin D on insulin levels." (PMID 38137858, 2023). "Importantly, aberrant accumulation of proinsulin relative to insulin is observed in islets from pancreatic tissue from human organ donors with autoantibody positivity, type 1 diabetes, and type 2 diabetes." (PMID 37537395, 2023). "In type 2 diabetes, both insulin secretion and action are impaired." (PMID 38203600, 2023).
type 2 diabetes (continued). "The impairments in adipose tissue insulin sensitivity may contribute to the development of type 2 diabetes." (PMID 39434962, 2023). "The fetal insulin hypothesis proposes that low birthweight and type 2 diabetes (T2D) in adulthood may be two phenotypes of the same genotype." (PMID 37949941, 2023). "Distinct from the Gs-coupled receptors therapeutically targeted to treat insulin deficiency in type 2 diabetes, and in spite of the considerable evidence for the positive role of FFA1 for insulin secretion, the therapeutic potential of FFA1 remains controversial." (PMID 37217659, 2023). "Anti-diabetic activity: Bromophenols may help to regulate blood sugar levels and improve insulin sensitivity, which may be beneficial for people with type 2 diabetes." (PMID 37367648, 2023). "Metformin is the most commonly prescribed drug for the treatment of type 2 diabetes (T2DM) as well as other indications requiring insulin-sensitizing drugs, such as polycystic ovary syndrome (PCOS), presenting with insulin resistance, hyperandrogenemia and female infertility." (PMID 37628660, 2023). "Over the years, animal and cell culture studies have shown that n-3 PUFA may prevent type 2 diabetes through anti-inflammatory properties, insulin signaling, changing cell membrane function and controlling expression of glucose metabolism genes." (PMID 36839358, 2023). "Most of the population had type 2 diabetes, and 54.3% were on insulin treatment." (PMID 36793073, 2023). "Furthermore, skeletal muscle contributes to approximately one-third of postprandial glucose disposal, and its diminished response to insulin is characteristic of type 2 diabetes." (PMID 36894534, 2023). "In a cross-sectional analysis, individuals with type 2 diabetes (T2D) had higher Cer18:0, Cer20:0, Cer24:1, and total ceramides levels, where elevated Cer18:0 levels were inversely correlated with insulin sensitivity and directly correlated with circulating TNF-α levels." (PMID 36904216, 2023). "The trajectories of fasting and postload glucose levels, as well as the trajectories of Homeostatic Model Assessment (HOMA) evaluations of insulin sensitivity and insulin secretion (β-cell function) leading up to the onset of type 2 diabetes have been elucidated in the British Whitehall II cohort." (PMID 38115080, 2023). "- Type I diabetes or uncontrolled Type II diabetes defined as insulin dependent." (PMID 37284481, 2023). "We typically think of type 2 diabetes (T2D) as being the result of years of insulin insensitivity (insulin resistance) leading to beta-cell secretory dysfunction, while type 1 diabetes (T1D) results mainly from a failure of insulin secretion due to loss of beta-cells from autoimmunity." (PMID 37409234, 2023). "Sleep's impact on insulin sensitivity is one of the main factors tying it to type 2 diabetes." (PMID 38050514, 2023). "Several studies found that various doses of intranasal insulin lead to a mild decrease in blood glucose levels in healthy young adults, whereas no such effect was found in overweight or obese patients and patients with type 2 diabetes." (PMID 37234022, 2023). "In summary, different components of a healthy lifestyle likely have a synergistic effect on systemic inflammation, oxidative stress, glycaemic index, satiety, insulin resistance, and weight maintenance, all of which contribute to the development of type 2 diabetes." (PMID 37794451, 2023). "The inhibition of VEGF-B in type 2 diabetes patients is affecting insulin sensitivity." (PMID 37692568, 2023). "Consequently, in 1948, type 2 diabetes was relatively uncommon, with the majority of cases being type 1 diabetes requiring insulin therapy." (PMID 38130527, 2023). "The present discoveries further raise the possibility that therapeutic strategies can be developed which will combat type 2 diabetes by enhancing endothelial cell insulin transport, thereby increasing insulin delivery and ultimately glucose disposal in skeletal muscle." (PMID 37591837, 2023).